FOXP3 (forkhead box P3)
Diseases named in the same sentence as FOXP3 in open-access papers (continued):
Sharing a sentence is not in itself a finding about the gene and the disease.
colorectal cancer (189 papers, 2006 to 2026). A primary or metastatic malignant neoplasm that affects the colon or rectum. "In tumors with strong inflammatory signatures, such as oropharyngeal, hypopharyngeal, esophageal, and colorectal cancers, high FOXP3 expression is associated with a favorable prognosis." (PMID 40806346, 2025). "We consulted the NCBI database and found that the rs3761548 polymorphism in the Foxp3 gene has been linked to malignancies such as colorectal cancer, gastric adenocarcinoma, and endometrial cancer." (PMID 39935826, 2025). "Reduced CD3+FoxP3+ T cells were also observed in the spleens of IRAK3-deficient mice in a colorectal cancer model." (PMID 40370470, 2025). "Tumours with high Tregs were often associated with poor prognosis in many cancers, however, in colorectal cancer contrary to others the high abundance of FOXP3+ Tregs was associated with a good prognosis." (PMID 38532103, 2024). "Our results regarding RSS2 in rectal tumours support the concept that low FOXP3+ Treg infiltration in tumours is associated with poor outcomes in colorectal cancers." (PMID 38532103, 2024). "There are many studies on immune cell infiltration in colorectal cancer, including FoxP3+-regulatory T cells, CD66b+ tumor-associated neutrophils, and CD163+ tumor-associated macrophages." (PMID 37232465, 2023). "A previous study on colorectal carcinoma reported that abundant infiltration of low-FOXP3-expression T cells was associated with significantly better prognosis than infiltration of high-FOXP3-expression Treg cells." (PMID 37573372, 2023). "Foxp3+ Treg cells are enriched in the human colorectal cancer TME and are associated with poor prognosis." (PMID 35517410, 2022). "Aberrant expression of FOXP3 in colorectal cancer is related to immune overdrive in a high-risk subpopulation." (PMID 36160018, 2022). "In contrast, a local accumulation and Foxp3 (+) cell density is associated with an improved survival rate and is considered as a good independent prognostic biomarker in the initial stage of colorectal cancers." (PMID 33919941, 2021). "In colorectal cancer, FoxP3+ T lymphocyte infiltrates have been associated with good and bad prognosis by different studies." (PMID 34440038, 2021). "Recently, tumor CD274 (PD-L1) expression is inversely associated with FOXP3+ cell density in colorectal cancer tissues and FOXP3 is expressed significantly higher in cytolytic-high colorectal tumors." (PMID 34768829, 2021). "Studies in humans with colorectal cancer have found an association between a low CD3+/FoxP3 ratio and shortened survival." (PMID 33712002, 2021). "Increased numbers of FoxP3+Helios+ Tregs expressing upregulated levels of ICs have been associated with poor disease prognosis in cancer patients, for example, those with colorectal cancer." (PMID 31614877, 2019). "Recently, investigators have evaluated that the tumor-infiltrating FOXP3+ Tregs are linked to colorectal cancer progression and outcome." (PMID 30013992, 2018). "In contrast, TH2–type cells and immune-suppressive FoxP3+ regulatory T-cells have been implicated in metastasis formation in colorectal cancer and other solid tumors." (PMID 29163806, 2017). "Although tumour-infiltrating Foxp3+ cells are associated with poor prognosis in most solid cancers, their presence in colorectal cancer has proven to be a good prognostic factor in several independent studies." (PMID 28177891, 2017). "Our data further reveal a correlation of Il17a and Rorc with Foxp3 expression in ovarian cancer-associated and colorectal cancer-infiltrating cells (the expression of Il17a in primary colorectal cancer cells is undetectable), respecitvely." (PMID 28290453, 2017). "High FoxP3+ Tregs infiltration was associated with significantly longer cancer-specific survival in colorectal cancer (OR 0.63, 95% CI 0.48 to 0.88, P = 0.007) and endometrial cancer (OR 0.42, 95% CI 0.24 to 0.73, P = 0.002)." (PMID 26462617, 2015).
colorectal cancer (continued). "FOXP3 has been reviewed to be associated with either good or neutral prognostic effect in colorectal cancer." (PMID 25906747, 2015). "The current study provides for the first time evidence of a significantly increased tumor-related expression of the transcription factor Foxp3 in colorectal cancer cells that is associated with adverse prognosis." (PMID 23382847, 2013). "As expected, low numbers of these Foxp3+ Tregs have been associated with improved patient outcome in breast and colorectal cancers." (PMID 21864372, 2011). "A recent study of FoxP3+ Treg in colorectal cancer also showed high Treg numbers to be associated with improved survival." (PMID 19732435, 2009). "Likewise, an immune-MPE study have shown that omega-3 PUFAs reduce the risk of colorectal carcinoma, specifically for subtypes with high FOXP3+ regulatory T cell counts." (PMID 39653811, 2025). "Besides, FOXP3+ Treg cell infiltration is generally associated with favorable prognosis in colorectal cancers, and high infiltration of Th17 cells was reportedly linked with poor prognosis in this disease." (PMID 39232704, 2024). "This includes histone deacetylases (HDAC) inhibition, increased expression of the transcription factor forkhead box P3 (FoxP3) specific to regulatory T cells (Tregs), and the anti-inflammatory cytokine IL-10, which help mitigate inflammation associated with colorectal cancer." (PMID 39770115, 2024). "Infiltration of CD163+ tumor-associated macrophages, FoxP3+-regulatory T cells, and CD66b+ tumor-associated neutrophils in colorectal cancer tissues may be related to the differentiation of tumor cells." (PMID 37232465, 2023). "The number of CD163+ tumor-associated macrophages, FoxP3+-regulatory T cells, and CD66b+ tumor-associated neutrophils in colorectal cancer tissues was different, and the level of CD163+ tumor-associated macrophages was the highest while the level of FoxP3+-regulatory T cells was the least." (PMID 37232465, 2023). "Furthermore, they proposed that those subsets contributed in opposing ways to colorectal cancer outcomes with the FOXP3-low subset associating with improved patient survival." (PMID 36010856, 2022). "Interestingly, colorectal cancers characterized by abundant infiltration with highly stable Foxp3(hi) Tregs were associated with a worse prognosis than those with low-stability Tregs." (PMID 34248973, 2021). "Foxp3 (+) cells infiltrating colorectal carcinomas could be associated with their capacity to suppress tumor-promoting inflammatory immune response caused by infectious stimuli from bacterial translocation through the mucosal barrier." (PMID 33919941, 2021). "Additionally, IL-17A+FoxP3+ T cells are found in colorectal cancer human tissue samples, and have been demonstrated to induce colorectal cancer associated cell markers." (PMID 31681327, 2019). "Similarly, diseases like rheumatoid arthritis or colorectal cancer are associated to the expression of IL-17+Foxp3+ Treg cells or RORγt + Foxp3+ Treg cells, respectively." (PMID 31481957, 2019). "However, other studies reported that increased frequency of FoxP3+ Tregs was associated with improved prognosis in colorectal cancer and head and neck squamous cell carcinoma." (PMID 31138162, 2019). "The aim of the study is the assessment of the intensity of the infiltration of tumor-associated macrophages (TAMs) CD68+/iNOS− and Tregs CD8+/FoxP3+ in colorectal cancer (CRC) patients as prognostic factors with respect to disease-free survival (DFS) and overall survival (OS)." (PMID 28343267, 2017). "In colorectal cancer, a high tumoral FoxP3 expression was already associated with poor prognosis." (PMID 24797069, 2014). "By contrast, a high density of FOXP3 was associated with improved survival in tumors related to the lymphoid system, such as follicular lymphoma and classical Hodgkin lymphoma, or tumors exposed to a bacterial inflammatory environment, such as colorectal cancer." (PMID 30153850, 2018).
colorectal cancer (continued). "Our results align with previous studies showing that high FOXP3 expression is associated with favorable prognosis in OSCC and HPV-negative HNSCC, as well as in ovarian and colorectal cancer." (PMID 40806346, 2025). "All of these subtypes have been associated in the majority of previous studies with a more favorable prognosis, while FoxP3 expression has been correlated with colorectal cancer progression." (PMID 41008839, 2025). "LAP+CD4+ Foxp3+ T cells are a subgroup of Tregs and are enriched in blood and tumor tissues of patients with colorectal cancer." (PMID 40053558, 2025). "Gallic acid, a constituent of GSE, was found to enhance intratumoral CD8+ T cells while suppressing tumor-infiltrating FOXP3+ Treg cells in a murine model of colorectal carcinoma." (PMID 40843004, 2025). "FOXP3(+) Treg density in normal and tumor tissue had stronger prognostic significance in colorectal cancer compared with CD8(+) and CD45RO(+) lymphocytes." (PMID 39664195, 2024). "In the studies included in our research on the relationship between TLS and FOXP3 expression levels, there were 1 colorectal cancer study, 2 hepatocellular carcinoma studies, and 1 pancreatic cancer study, all of which showed significant heterogeneity." (PMID 39259184, 2024). "The studies we included in our research investigating the relationship between TLS and FOXP3 expression levels consist of one study on colorectal cancer, two studies on liver cancer, and one study on pancreatic cancer." (PMID 39259184, 2024). "Legumain localizes to the nucleus in the setting of colorectal cancer and can cleave the nuclear protein FOXP3 in regulatory T-cells to inhibit T-cell differentiation." (PMID 38199506, 2024). "It was found that Foxp3+ Treg cells were capable of inducing colorectal cancer cells to become cancer-initiating cells." (PMID 39073490, 2024). "Treg cells are suggested to inhibit protumorigenic effects by suppressing proinflammatory and tumor-promoting abilities of Th17 cells, providing a possible explanation for the favorable prognostic role of FOXP3+ Treg cells in colorectal cancer." (PMID 39232704, 2024). "For example, colorectal carcinomas with abundantly infiltrated FOXP3(low) T cells demonstrated a much better prognosis than tumors with predominant FOXP3(high) Treg infiltration." (PMID 38481999, 2024). "FN enhanced the suppressive immune microenvironment with high depletion of CD8+ T cells and enrichment of FoxP3+ regulatory T cells in human colorectal cancer cases." (PMID 36960042, 2023). "FOXP3 levels are also higher in colorectal cancer tissues than in normal colorectal tissues, and its expression is associated with a poor prognosis compared to patients with low FOXP3 expression." (PMID 37176567, 2023). "Saito and colleagues demonstrated that, in colorectal cancer, two different Treg subsets can be distinguished by different levels of expression of FOXP3." (PMID 36010856, 2022). "(A) Representative pictures of T cell infiltration (CD4, CD8, FOXP3) in colorectal cancer (CRC) tissues for VPS9D1-AS1 quantification." (PMID 36458816, 2022). "Natural killer cells (NKs) and Th17 cells were negatively correlated with Tregs in one and three lung cancer studies respectively, as well as FOXP3+ tumor cells in one colorectal cancer article." (PMID 35740658, 2022). "The prognostic relevance of FoxP3+ tumour-infiltrating Treg in colorectal cancer (CRC) and rectal cancer (RC) has been a frequently studied albeit controversial subject." (PMID 35140715, 2022). "Concomitantly, Michel and colleagues performed a systematic evaluation of the FOXP3+ immune infiltration and MMR deficiency, revealing that MMRd/MSI-High (MSI-H)-deficient colorectal cancer displayed increased FOXP3-positive cells." (PMID 34072037, 2021).
colorectal cancer (continued). "In recent years, Foxp3+ T cells have been found in many tumors, such as HCC, pancreatic ductal adenocarc, colorectal cancer, gastric cancer, and esophageal cancer, suggesting that Foxp3+ T cells participated in the tumor progression." (PMID 34566989, 2021). "Taken together, these data warrant further investigation on the prognostic potential of FoxP3+ T lymphocytes in colorectal cancer." (PMID 34440038, 2021). "FOXP3-TSDR demethylation in tumor-infiltrating CD4+ T cells of colorectal cancer patients was mediated by the increase of TET-2 that catalyzed 5-methylcytosine (5mC) conversion to 5-hydroxymethylcytosine (5hmC)." (PMID 34539668, 2021). "Recently, it was reported that tumor-infiltrating Foxp3 Tregs predict a favorable outcome in colorectal cancer patients." (PMID 32230738, 2020). "Similar to CD4+FOXP3+ Treg, CD8+FOXP3+ T cells with apparent immunosuppressive capacity have been reported in human malignancies such as colorectal cancer and ovarian cancer." (PMID 33013886, 2020). "It has been reported that FoxP3 expression is increased in thyroid cancer, hepatocellular carcinoma, colorectal cancer, cervical cancer and oral squamous cell carcinoma and promotes tumor progression." (PMID 31864387, 2019). "The FOXP3+ T cells were analyzed separately because its prognostic effect on colorectal cancer is controversial." (PMID 31118034, 2019). "Not only CEACAM8+ cells, but also CD3+, CD8+, and FOXP3+ cells were observed in colorectal cancer tissues." (PMID 31456937, 2019). "Since colorectal cancer has shown different prognostic meaning for FOXP3+ Treg compared with other organs in previous studies, and CD103+ immune cells are widely expressed in Tregs, the inclusion of some organs has the potential to shift the result." (PMID 30846807, 2019). "According to a previous report, the prognostic role of FOXP3+Treg in colorectal cancer is controversial." (PMID 31118034, 2019). "In the immunosuppressive microenvironment of ovarian and colorectal cancer, a high prevalence of unusual Foxp3+CD8+ regulatory T cell has been described." (PMID 30258117, 2018). "In prostate cancer patients, studies have found tumor-infiltrating regulatory lymphocytes with the same phenotype (CD8+CD25+FoxP3+) as the one observed in lymphocytes of colorectal cancer patients." (PMID 30155493, 2018). "Meanwhile, higher percentages of intratumoral FoxP3+ cells are revealed to be correlated with a favorable outcome in colorectal cancer patients." (PMID 29312592, 2017). "Conversely, high Foxp3 expression of the colorectal cancer cells was correlated with unfavorable prognosis compared with cases that had low Foxp3 expression." (PMID 28923073, 2017). "Higher immune gene expression of IL-17 was also been proven to be a determinant in mismatch repair proficient colorectal cancer, and so was FOXP3." (PMID 28029650, 2017). "Nevertheless, in four of these studies in which double labeling of FoxP3 combined with CD4+, CD25+ or CD8+ was applied, the double-positive T cells were generally associated with a poor prognosis except colorectal cancer." (PMID 26604855, 2015). "For gastrointestinal cancers including hepatocellular carcinoma, colorectal cancer and gastric cancer, the prognostic value of FoxP3+ Tregs was completely different." (PMID 26462617, 2015). "The demonstration that FOXP3 expression positively associated to a better EFS and OS of high-risk NB patients is in agreement with previous reports in head and neck and colorectal cancer patients." (PMID 26161395, 2015). "Our pooled analysis of 8 studies involving 3972 patients established that high number of intratumoral FoxP3+ Tregs was associated with longer OS and DFS in colorectal cancer." (PMID 26462617, 2015). "Accordingly, Foxp3+ TILs coincided with generally favorable prognosis in colorectal cancer but poor prognosis in hepatocellular cancer." (PMID 24276989, 2014).
colorectal cancer (continued). "In a recent published meta-analysis, it was shown that tumor-infiltrating FOXP3+ T cells correlated with poor prognosis in hepatocellular carcinoma and gastric cancer, but good prognosis in colorectal cancer." (PMID 25191901, 2014). "In order to investigate the role of LAP in human CD4+Foxp3+ Tregs, we designed a cross-sectional study that involved 42 colorectal cancer (CRC) patients." (PMID 25268580, 2014). "Some studies investigating colorectal cancer concluded that FoxP3+ T cells correlated with a good prognosis, whereas other studies found no prognostic association or even a bad prognostic claim." (PMID 24827118, 2014). "In this study we initially undertook to evaluate the prognostic values of different TIL (CD3+, CD8+, FoxP3+) densities in colorectal cancers with microsatellite instability." (PMID 23613769, 2013). "In many colorectal cancer studies, the observation that increased Foxp3+ Treg cells correlate with good prognosis is particularly intriguing." (PMID 23874336, 2013). "Previous studies have examined the suppressive capacities of CD8+CD25+Foxp3+ T cells in colorectal cancer tissues." (PMID 23382847, 2013). "Here, we demonstrate that the expanded FOXP3+ T-cell population inpatients with colorectal cancer, CLL, MGUS, MM, follicular lymphoma, and Hodgkin's disease are exclusively CD127low Treg cells andwere strongly suppressive." (PMID 21904560, 2011). "Recent data also indicated that the presence of Foxp3+ T cells in tumour draining lymph nodes of colorectal cancer patients correlated with disease progression." (PMID 21864372, 2011). "In colorectal cancer, most studies are in line with our findings indicating that a high number of FoxP3 Tregs is a favourable prognostic factor for disease-free and overall survival time." (PMID 21179245, 2010). "In these patients CD8+CD25+Foxp3+ T cells were detectable in the blood and more prominently in the colorectal cancer tissue with a phenotype closely resembling the CD8+Foxp3+ T cells from our transgenic mouse model." (PMID 20975955, 2010). "Very recently, a subpopulation of CD8+CD25+Foxp3+ suppressive T cells in patients suffering from colorectal cancer was identified." (PMID 20975955, 2010). "These technical considerations notwithstanding, there is mounting evidence that tumor-infiltrating FoxP3+ cells are associated with a favorable prognosis in EOC, colorectal cancer, head and neck cancer, and lymphoma [14,33,-36,99-102]." (PMID 19641607, 2009). "Our results show that the elevated number of CD8-positive lymphocytes found in MSI-H colorectal cancers is paralleled by an enhanced infiltration with CD8-negative FOXP3-positive cells." (PMID 18985040, 2008). "However, in certain unique tumor types, such as colorectal cancer as well as few head and neck tumors, heightened intratumoral FOXP3 expression indicates a more favorable prognosis." (PMID 38500876, 2024). "However, FOXP3-expressing T cells are heterogenous in colorectal cancer, and certain types of FOXP3-expressing T cells (FOXP3lo) and activation-induced FOXP3-expressing T cells have been reported as non-immunosuppressive T cells." (PMID 38339307, 2024). "However, some researchers indicated that FOXP3 is one of the unfavorable prognostic factors in colorectal cancer." (PMID 36693070, 2023). "However, in colorectal cancer patients inflammatory infiltrate response, the the upregulate of STAT was negatively associated with Foxp3+ T lymphocytes and potential to relieve local and systemic inflammation." (PMID 36226375, 2023). "PD-L1 expression in colorectal cancer tissues was negatively correlated with FOXP3 + cell density, suggesting that PD-L1-expressing cancer cells may affect regulatory T cells in the tumor microenvironment." (PMID 37880682, 2023).